ILK (integrin linked kinase)
Diseases named in the same sentence as ILK in open-access papers (continued):
Sharing a sentence is not in itself a finding about the gene and the disease.
bladder cancer (13 papers, 2013 to 2023). "Hsp27 is also a target of integrin-linked kinase (ILK), which promotes the migration of bladder cancer cells." (PMID 36686743, 2022). "Further research indicated that miR-145 indirectly regulates the Akt pathway by directly targeting Integrin-Linked Kinase (ILK), and co-treatment with miR-143 and miR-145 synergistically inhibited cell growth in bladder cancer cells." (PMID 25124875, 2014). "In vitro and in vivo, as well as clinical studies, have implicated ILK over-expression in invasive bladder cancer playing an important role in epithelial-to-mesenchymal transition." (PMID 25333694, 2014). "One study showed that Rac1 regulates bladder cancer cell invasion and actin reorganization downstream of integrin-linked kinase (ILK)." (PMID 24312263, 2013). "ILK gene expression is correlated with tumor invasiveness of bladder cancer in humans, and plays an important role in metastasis, predisposing tumors with high ILK expression to a more aggressive phenotype." (PMID 24018887, 2013). "The data provided evidence that ILK could be a valuable therapeutic and diagnostic target for bladder cancer." (PMID 27576342, 2016). "Another report indicates that ILK migt be downregulated by synergistic interaction of miR-145 and miR-143, projecting on inhibiting growth of bladder cancer cells." (PMID 35089438, 2022). "Presented results show that ILK pathway regulates the cadherin switch of bladder cancer through multiple mechanisms, including transcriptional and posttranslational regulation." (PMID 27683053, 2016). "This research first proved that direct binding of RI and ILK regulated EMT through ILK signaling pathway in bladder cancer." (PMID 27576342, 2016). "Our previous experiment demonstrated that ILK siRNA inhibited the growth and induced apoptosis of bladder cancer cells as well as increased the expression of Ribonuclease inhibitor (RI), an important cytoplasmic protein with many functions." (PMID 27576342, 2016). "The results showed that the ILK significantly facilitated the growth of bladder cancer, whereas, RI obviously suppressed xenograft tumor." (PMID 27576342, 2016). "The aim of the present study was to elucidate the mechanism of ILK-induced EMT and cadherin switch as a hallmark, in bladder cancer cells." (PMID 27683053, 2016). "The siRNA reduction of ILK expression had significant effects on PARP-1 protein levels in the bladder cancer cell line T24." (PMID 27683053, 2016). "To gain insights into the expression of ILK and RI in tumor tissue from nude mice and human bladder cancer, we performed immunofluorescent assay to determine the two kinds of protein level in the specimens." (PMID 27576342, 2016). "Western blot analysis of subcellular fraction showed that Snail, Twist-1, and Zeb-1 protein nuclear translocation was inhibited in T24 bladder cancer cells depleted of ILK." (PMID 27683053, 2016). "The data suggest that ILK expression was negatively correlated with RI levels in the bladder cancer specimens from nude mice and human." (PMID 27576342, 2016). "ILK knockdown by siRNA suppressed N-cadherin expression and increased re-expression of E-cadherin in bladder cancer cells." (PMID 27683053, 2016). "This research is aimed at further revealing the molecular mechanisms of interplay between ILK and RI as well as supplying new methods to the therapy of carcinoma of bladder." (PMID 27576342, 2016). "Importantly, in bladder cancer, ILK expression is exceptionally up-regulated, which can expedite the malign biological behaviors of cancer cells." (PMID 35029589, 2022). "The mechanism associated with the role of ILK in tumor progression of bladder cancer is not well understood." (PMID 27683053, 2016). "In this report, we studied the role and mechanism of ILK in EMT of human bladder cancer." (PMID 27683053, 2016). "They indicate that ILK regulates the EMT of bladder cancer and the mechanism depends on cell types." (PMID 27683053, 2016).
bladder cancer (continued). "The fact that higher level of RI and lower level of ILK in paired normal tissues suggest that RI could be required to regulate ILK for suppression of bladder cancer." (PMID 27576342, 2016). "In this study, the effects of re-expression of E-cadherin on mRNA and protein level were markedly higher in HCV29 compared with control nonsilencing RNA, and the re-expression of E-cadherin on protein level was slightly visible upon silencing of ILK in T24 bladder cancer cells." (PMID 27683053, 2016). "In addition to showing promise as an indicator of more aggressive, metastatic disease, ILK has displayed rather significant potential as a therapeutic target in the treatment of bladder cancer." (PMID 24018887, 2013). "To elaborate on the downstream target of miR-542-3p in bladder cancer, we searched StarBase database, TargetScan database and miRDB database, and 108 potential genes were predicted to have the complementary binding sites with miR-542-3p, and ILK was among the candidate targets." (PMID 35029589, 2022). "Six invasive bladder cancer cells (J82, KK47, KU7, T24, TCCSUP, and UMUC3) that exhibit mesenchymal morphology were found to have high ILK protein expression, high ZEB1 expression, and low E-cadherin expression." (PMID 37627900, 2023). "Finally, ILK has been widely suggested as a potential therapeutic target not only in human malignancies, but also in fibrosis of kidney, lung, prostate, or bladder cancer; Alzheimer disease; inflammatory renal diseases; nephrogenic diabetes insipidus (NDI) or cardiovascular diseases." (PMID 35089438, 2022). "Although ILK is believed to be a key factor in EMT, its role in bladder cancer progression is not completely understood." (PMID 27683053, 2016).
glioblastoma (13 papers, 2010 to 2024). The most malignant astrocytic tumor (WHO grade IV). "We find that a drug that targets integrin-linked kinase also affects Abelson kinase levels and its localization to the centrosome in dividing glioblastoma cells." (PMID 37508338, 2023). "The vital role of ILK in the process of mitosis was supported in studies on the inhibition of ILK, which caused a G2-M-phase arrest in glioblastoma-cell lines." (PMID 35089438, 2022). "IKVAV is shown to induce glioblastoma apoptosis by immobilizing β1-integrin at the cell membrane, activating integrin-linked kinase and inhibiting focal adhesion kinase." (PMID 33014989, 2020). "We found that β1 integrin as well as the integrin-associated proteins PINCH1 and ILK were mainly located in focal adhesions of glioblastoma cells, whereas ILKAP was expressed in the cytoplasm and nucleus." (PMID 26460618, 2015). "In addition, it was indicated that integrin-linked kinase (ILK) was required to mediate feedback activation of the PI3K/AKT pathway following MEK suppression in glioblastoma cells." (PMID 36686779, 2022). "In addition, integrin linked kinase (ILK) is required to activate feedback activation of PI3K-AKT pathway following MEK suppression in glioblastoma cells." (PMID 27563827, 2016). "In past studies, we found that anti-ILK therapies in vitro increased apoptosis in retinoblastoma and glioblastoma cell lines, as measured using propidium iodide labelling and FACS analysis." (PMID 37508338, 2023). "Here, we expressed wild-type (WT) and kinase-dead (KD) FLAG-tagged ILK constructs in glioblastoma and immunostained cells for pericentrin and FLAG." (PMID 37508338, 2023). "ABL and ILK are highly expressed in glioblastomas and both have been individual chemotherapeutic targets for this tumour model." (PMID 37508338, 2023). "Exposure of glioblastoma cells to ILK and ABL inhibitors, in combination, increases cytotoxicity and aberrant mitotic events over individual inhibitors alone." (PMID 37508338, 2023). "The proto-oncogenes ABL and ILK are promising combination drug targets for solid tumours such as glioblastomas as both kinases have a role in their progression." (PMID 37508338, 2023). "The inhibitory effect of ILK and control of tumorigenesis has been reported in regard to glioblastoma, but understanding its potential in high-grade meningioma remains unexplored." (PMID 37887327, 2023). "Another study has found that inhibiting ILK in retinoblastoma and glioblastoma cell lines induced senescence markers." (PMID 34163519, 2021). "Among the signaling pathways most changed in the SCC15CatGFP plus population, axonal guidance, glioblastoma multiforme, ILK, and integrin signaling pathways received special attention in the light of cancer–stroma interactions during invasion and metastasis." (PMID 35008571, 2021). "In line with previous studies, our analysis showed that PINCH1 and ILK were significantly overexpressed in glioblastoma biopsies compared with normal brain tissue." (PMID 26460618, 2015). "Glioblastoma cell viability following drug exposure was examined to determine whether chemotherapeutic drugs, targeting ILK and ABL in combination, were more efficacious than individual drugs alone." (PMID 37508338, 2023). "Also, in different cancer models such as retinoblastoma and glioblastoma cell lines, ILK inhibition by either QLT-0267 or ILK RNA interference increases SA-β-gal in Rb-positive cells." (PMID 34163519, 2021). "Genetic depletion of ILK expression or pharmacologic inhibition of ILK with an ILK inhibitor, Compound 22, blocked ligand-independent c-Met phosphorylation in the presence of fibronectin, and treatment with Compound 22 also reduced adhesion and spreading of U87 glioblastoma cells on fibronectin." (PMID 35804980, 2022). "ILK inhibitor effects on survival correlated with its ability to decrease cytosolic ABL levels and inhibit ABL’s localization to mitotic centrosomes in glioblastoma cells." (PMID 37508338, 2023).
glioblastoma (continued). "Drug-concentration viability assays (i.e., MTT assays) indicate that ILK and ABL inhibitors in combination decreased the viability of glioblastoma cells over the ILK drug QLT-0267 alone." (PMID 37508338, 2023). "In this study, we examined the relationship between ILK and ABL at mitotic centrosomes in glioblastoma cell lines." (PMID 37508338, 2023). "The purpose of this study is to further characterize the relationship between ILK and ABL in centrosome function and cell survival of mitotically dividing glioblastoma cells." (PMID 37508338, 2023). "To analyze the impact of PINCH1, ILK and ILKAP on cell survival, we performed efficient siRNA-mediated depletion in four different glioblastoma cell lines." (PMID 26460618, 2015). "In line with this knowledge, we found decreased basal and radiation survival of glioblastoma cells after PINCH1 depletion and far less after ILK targeting." (PMID 26460618, 2015). "Further, a mutant glioblastoma cell line lacking the PTEN gene was associated with the activation of PI3K-dependent signaling and suppression of the ILK pathway." (PMID 38543160, 2024). "Finally, we find that ILK inhibition decreased ABL levels at the centrosome and this correlates with aberrant mitotic events and survival effects in glioblastoma." (PMID 37508338, 2023). "Indeed, increased cytotoxicity of ILK and ABL inhibitors in combination correlates with aberrant mitotic events in glioblastoma cells." (PMID 37508338, 2023).
hepatocellular carcinoma (11 papers, 2010 to 2025). A malignant tumor that arises from hepatocytes. "In a mouse model of hepatocellular carcinoma, transformation with kinase-inactivated integrin-linked kinase (KI-ILK) partially restored the sensitivity to anti-EGFR treatment." (PMID 25050175, 2014). "In hepatocellular carcinoma, ILK activated Akt through phosphorylating Akt at Ser473, resulting in EMT of liver epithelial cells and radioresistance and chemoresistance of hepatocellular carcinoma cells." (PMID 27034956, 2016). "It has been found that the overexpression of kinase-inactive ILK increases the sensitivity of EGFR-resistant hepatoma cell lines to the EGFR inhibitors erlotinib, gefitinib and cetuximab in vitro and in vivo." (PMID 21060779, 2010). "Consistent with a role for ILK in mediating EGFR tyrosine kinase inhibitor (TKI) resistance, xenograft models of EGFR inhibitor-resistant human hepatocellular carcinoma cell lines found that inhibiting ILK activity increased the sensitivity of cells to EGFR inhibition." (PMID 34373451, 2021). "In hepatocellular carcinoma (HCC), transfection with an ILK expression vector was able to recover the decreased expression of its downstream genes AKT and GSK3β phosphorylation, and affected cell proliferation and apoptosis." (PMID 33531984, 2021). "Although ILK has been well characterized in many malignancies, its role in hepatocellular carcinoma (HCC) is still largely unknown." (PMID 21347395, 2011).
heart failure (10 papers, 2011 to 2024). Inability of the heart to pump blood at an adequate rate to meet tissue metabolic requirements. "This was demonstrated in a recent study, in which the genetic model of heart failure (cardiac-specific integrin-linked kinase (ILK) knockout) mice were injected intraperitoneally with a neutralizing anti-mouse OPN polyclonal goat immunoglobulin G." (PMID 31816901, 2019). "Moreover, the loss of ILK in murine models leads to spontaneous development of cardiomyopathy and heart failure, characterized by a significant disruption in cell adhesion and a decrease in Akt phosphorylation, crucial for cardiac stress response." (PMID 39337275, 2024). "Aided by the ILK-deficient zebrafish heart failure mutant (msq), we identified in an automated small compound screen the protein phosphatase inhibitors calyculin A and okadaic acid leading to significantly restored pump function of the zebrafish heart via reconstituting PKB phosphorylation." (PMID 30463267, 2018). "Our results corroborate the recent animal model observations that have shown that ILK-mediated Akt/PKB activation is a key pathway for mediating cardiac dysfunction especially during heart failure and repair." (PMID 21625516, 2011). "Understanding the ILK related mechanism of cardiac maladaptation leads to a new strategy for treatment of heart failure after infarction." (PMID 21949693, 2011). "The present study shows that ILK is dramatically elevated in human DCM hearts further establishing a potential role of ILK in heart failure." (PMID 21625516, 2011). "Our findings suggest that cardiac ILK treatment can reduce autophagic activity, and this may contribute to delaying, or even reversing, the progression of heart failure." (PMID 22348065, 2012). "Therefore we suggest that in the process of cardiac remodeling, impaired ILK related angiogenesis is the key feature when heart failure occurs." (PMID 21949693, 2011). "Understanding the ILK related mechanism of cardiac maladaptation may lead to a new strategy for treatment of heart failure after infarction." (PMID 21949693, 2011). "To further verify that down-regulation of ILK accelerated cardiac remodeling and heart dysfunction via affecting tissue angiogenesis; we observed the therapeutic effect of sustained ILK expression in heart failure." (PMID 21949693, 2011). "Since cardiac-specific knockout of ILK causes spontaneous cardiac failure while cardiac-specific knockouts of β1 integrin, melusin, or FAK require the stress of pressure overload to decompensate to cardiac failure, ILK likely has other signaling effectors to mediate several critical pathways." (PMID 21637377, 2011). "Therefore, consistent with previous report, Akt could be still activated by other signaling pathway in heart failure, though ILK expression and activity is already decreased." (PMID 21949693, 2011). "With the aim to enhance ILK-PKB signaling pathway in msq, we studied the impact of 32 small compounds derived from a phosphatase inhibitor library on ventricular FS in this heart failure model." (PMID 30463267, 2018). "However, at present it is not known whether ILK gene therapy may improve cardiac function in models of heart failure and in the absence of underlying cardiac ischemia." (PMID 22348065, 2012). "Once ILK expression was decreased, VEGF dependent angiogenesis was attenuated, leading to myocyte death and heart failure." (PMID 21949693, 2011). "In order to determine the level of the ILK and PINCH complex separately during heart failure, we performed co-immunoprecipitation studies." (PMID 21625516, 2011).
leukemia (10 papers, 2009 to 2022). A malignant (clonal) hematologic disorder, involving hematopoietic stem cells and characterized by the presence of primitive or atypical myeloid or lymphoid cells in the bone marrow and the blood. "Indeed, here we show that interactions of leukemic murine and human cells with the BMM via the fibronectin/integrin β3/integrin-linked kinase (ILK)-mediated signaling pathway influence leukemia progression and clinical outcome in BCR-ABL1T315I+ imatinib-resistant CML in vivo." (PMID 32439895, 2020). "Pharmacologic inhibition of ILK reduces Akt phosphorylation induced by stromal cells in the BMM and suppresses leukemia in the bone marrow, suggesting that ILK activity is critical to disease progression." (PMID 35804980, 2022). "Increasing evidence also points to the importance of ILK in leukemia, particularly in interactions between leukemic stem cells and the bone marrow matrix environment, suggesting a role of ILK in altered niche environments." (PMID 35804980, 2022). "For instance, co-culture of leukemia cells and bone marrow-derived stroma has been shown to lead to activation of the MAPK/ERK pathway and integrin-linked kinase (ILK), which phosphorylates Akt." (PMID 23437141, 2013). "ILK/Akt is likely critical for leukemia cell survival in bone marrow, and thus inhibitors of ILK have been proposed as an approach to simultaneously target both leukemia cells and leukemia-activated stromal cells." (PMID 23437141, 2013). "In addition, ILK expression levels positively correlate with the efficacy of Cpd22 in leukemia." (PMID 32260415, 2020). "Furthermore, fibronectin levels were significantly reduced in bone sections (P = 0.043) and levels of ILK, ILK pS246 and integrin β3 were higher in leukemia cell samples from most patients with BCR-ABL1T315I+ compared with BCR-ABL1+ CML, though inter-patient variability was observed." (PMID 32439895, 2020). "ILK can also be activated in leukemic cells, activating a feedback loop involving ILK/NF-κB, ending with CCL2 production and promoting leukaemia progression." (PMID 35629139, 2022). "The benefit of ILK inhibition may lie in the combination of increasing fibronectin levels in the BMM, as well as in the further increase of integrin β3 on leukemia cells." (PMID 32439895, 2020). "However, the branches of the ATM pathway, ILK signaling, NGF, PPAR and VEGF pathways were regulated oppositely in the adult and pediatric leukemia samples." (PMID 27870639, 2016). "In addition, ILK has been postulated to be a novel target in solid cancers and leukemia, though a connection to the BMM was not established." (PMID 32439895, 2020).